INS (insulin)
Diseases named in the same sentence as INS in open-access papers (continued):
Sharing a sentence is not in itself a finding about the gene and the disease.
type 2 diabetes (continued). "In a single-dose study with sotagliflozin at 300 mg in 12 patients with type 2 diabetes, there was a significant increase in GLP-1 and PYY, accompanied by a significant decrease in plasma glucose and insulin doses." (PMID 30819210, 2019). "Regarding the treatment of type 2 diabetes, PPAR-γ agonists decrease plasma fatty acid and hyperglycaemia by improving insulin sensitivity." (PMID 30867485, 2019). "Type 2 diabetes mellitus (T2DM), a metabolic disease characterized by hyperglycemia, is the results of reduced production and/or utilization of insulin, which also plays pivotal roles in the development of several important renal, cardiovascular, and neurological complications." (PMID 30387082, 2019). "Fasting serum insulin level and HOMA-IR index were both significantly (p < 0.01) higher for Model group than for NC group, consistently with type 2 diabetes symptoms." (PMID 30704063, 2019). "Given that the number of humans with type 2 diabetes and with metabolic disorders worldwide is still increasing, regulatory function of AMPK in both insulin secretion and action should be thoroughly explained." (PMID 31691163, 2019). "For the clinical treatment of type 2 diabetes, PACAP and adenylyl cyclase were also thought to be effective due to stimulation of insulin secretion and increased proliferation and differentiation of β cells." (PMID 31485258, 2019). "We observed only weak evidence of liability effects of type 2 diabetes (IVW P = 0.01), insulin secretion (IVW P = 0.04) and BMI (IVW P = 0.05) on chronotype." (PMID 30696823, 2019). "The islet in type 2 diabetes (T2D) is characterized by amyloid deposits derived from islet amyloid polypeptide (IAPP), a protein co-expressed with insulin by β-cells." (PMID 31213603, 2019). "Glucagon-like peptide-1 (GLP-1) is an incretin hormone that enhances insulin secretion, and GLP-1 agonists are used for glycemic control of type 2 diabetes." (PMID 30823876, 2019). "This population-based study explored the relationship between insulin analogues, chronic viral hepatitis, and HCC incidence among patients with newly-diagnosed type 2 diabetes who had been prescribed at least one kind of antidiabetic agent." (PMID 31200528, 2019). "Recently, natural products have been reported to improve insulin sensitivity via the activation of AMP-activated protein kinase (AMPK), which is believed to be a therapeutic target for the treatment of type 2 diabetes." (PMID 30939853, 2019). "The study demonstrated that the insulin requirement to maintain glycemia was markedly reduced by GLP-1, both in type 1 and type 2 diabetes." (PMID 31275243, 2019). "In pancreatic islet cells from type 2 diabetic patients, miR-124a was highly expressed, and its silencing in MIN-6 cells resulted in increased expression of genes involved in insulin secretion, such as Mtpn, Foxa2, Sirt1, and NeuroD1." (PMID 30974824, 2019). "The new drugs for type 2 diabetes SGLT-2i are reversible inhibitor of SGLT-2, leading to a reduction of renal glucose reabsorption and a decrease of plasma glucose, in an insulin-independent manner." (PMID 30857216, 2019). "Insulin therapy remains integral to treatment of type I diabetes mellitus (T1DM) and long-term type II diabetes mellitus (T2DM)." (PMID 29433560, 2018). "In conclusion, we demonstrate that plasma levels of 4-HHE are significantly increased in type 2 diabetes and that 4-HHE can significantly impede insulin action in vitro and in vivo." (PMID 29299636, 2018). "Among the pathways that were the most significantly enriched in the -omics data were several whose relevance to T2D is well established, such as Type II diabetes mellitus, PPAR signaling, insulin signaling, calcium signaling and chemokine signaling pathways." (PMID 29977601, 2018). "OLETF rats were initially studied primarily as a model of late onset type 2 diabetes, as older OLETF rats were not only obese but also hyperglycemic and insulin resistant." (PMID 30424007, 2018).
type 2 diabetes (continued). "Pancreatic fatty acid uptake and insulin-stimulated glucose uptake determined by PET were similar in the healthy and prediabetic or type 2 diabetic men at baseline, and remained unchanged after 2 weeks of exercise training." (PMID 29717337, 2018). "In type 2 diabetic patients, PST level is high and plays a crucial role in the negative regulation of insulin sensitivity." (PMID 29880906, 2018). "However, it is proven than continuous exposure to high insulin levels induces subtle derangements of intracellular receptor trafficking and insulin degradation, and these alterations may contribute to insulin resistance of hyperinsulinemic states, such as obesity and Type 2 diabetes." (PMID 30598026, 2018). "In erythrocytes from patients with type 2 diabetes, GSSG/GSH ratio were increased as compared to control subjects, which was reduced by insulin treatment in vitro, suggesting that activation of insulin signaling decreases GSSG/GSH ratio." (PMID 29402900, 2018). "The objective of this phase 3a, Semaglutide Unabated Sustainability in Treatment of Type 2 Diabetes (SUSTAIN) 5 trial was to demonstrate the superiority of once-weekly semaglutide (0.5 and 1.0 mg) vs placebo on glycemic control in patients with uncontrolled T2D on basal insulin therapy." (PMID 29688502, 2018). "Furthermore, ET-1 can directly interfere with cellular insulin signaling, enhance hepatic glucose output, diminish glucose uptake, impair insulin secretion and stimulate lipolysis in adipose tissue – effects directly contributing to hyperglycemia and development of type 2 diabetes." (PMID 29896159, 2018). "Body’s resistance to insulin and falling insulin production of pancreatic β cells are two main factors in HFD induced type 2 diabetes." (PMID 29755549, 2018). "Type 2 diabetes mellitus (T2DM) is a metabolic disorder typically characterized by hyperglycaemia, insulin resistance and insufficient insulin secretion from islet β‐cells." (PMID 28975620, 2018). "Hayashi demonstrates that intensive insulin therapy reduced serum small dense LDL particles and TG levels in type 2 diabetics." (PMID 29641741, 2018). "Type 2 diabetes mellitus (T2DM) is a metabolic disease resulting from insulin resistance, defects in insulin secretion or both, accounting for 90% diabetes." (PMID 29358755, 2018). "A similar pattern of insulin use was observed in our primary study of MDI and insulin pump use, with flash technology in type 2 diabetes managed with MDI and with standard CGM in type 1 diabetes managed by MDI or insulin pump therapy." (PMID 29273897, 2018). "Together these observations indicate that NPs support adaptative β-cell proliferation during early stages of increased insulin demand, here provoked by HFD as experimental model of type 2 diabetes." (PMID 30016962, 2018). "The expression of PI3K has been shown to be reduced in type 2 diabetic skeletal muscle, and pharmacological PI3K inhibition abolished insulin stimulation of glucose transport and DNA synthesis." (PMID 30469501, 2018). "Taken together with the reduction of HbA1c and the increase of both insulin sensitivity and β-cell function, the results of this study clearly justified the efficacy and safety of PIO in both lean and obese Chinese type 2 diabetes patients." (PMID 29536426, 2018). "Type 2 diabetes mellitus (T2DM) is a metabolic disorder characterized by hyperglycemia, insulin resistance, and insufficient insulin secretion from islet β cells." (PMID 29898400, 2018). "In type 2 diabetes (T2DM), there is an impaired response of peripheral tissues to insulin, known as insulin resistance, which promotes hyperinsulinemia and eventual beta cell dysfunction." (PMID 29867472, 2018). "Also, many of the cases reported as E10 may be individuals with type 2 diabetes using insulin." (PMID 29419786, 2018). "In addition, many patients with type 2 diabetes mellitus (T2DM) exhibit elevated glucagon levels and insufficient insulin secretion to control glucose levels." (PMID 29740399, 2018).
type 2 diabetes (continued). "Individuals with type 2 diabetes display increased hepatic synthesis of VLDL particles, resulting in elevated VLDL-triacylglycerol, presumably due to the impaired ability of insulin to suppress VLDL synthesis." (PMID 30145664, 2018). "In conclusion, patients initiating DPP-4 inhibitors as third-line therapy in type 2 diabetes appeared to have lower discontinuation and have less hypoglycemia when compared to patients starting NPH insulin." (PMID 29713649, 2018). "DM is a chronic disease characterized by increased blood glucose due to the pancreatic β cells unable to produce insulin as in the case of type 1 diabetes (T1D), or inability of the body to effectively utilize the insulin produced as in the case of type 2 diabetes (T2D)." (PMID 29449808, 2018). "In fact, the risk of hypoglycemia is a barrier to optimal treatment of type 1 diabetes (T1DM) and type 2 diabetes (T2DM), especially within the context of insulin therapy." (PMID 30479669, 2018). "Overall, increased O-GlcNAc appears to foster insulin insensitivity and hinder cellular glucose uptake making the HBP a novel therapeutic target in type II diabetes research." (PMID 30237786, 2018). "This single-center, randomized cross-over study explored for the first time the pharmacodynamic (PD) differences of the widely used basal insulin analogs detemir and glargine in WHO grade 2–3 obese individuals with type 2 diabetes." (PMID 30114246, 2018). "SNPs in this region have also been associated with type 2 diabetes mellitus (T2DM) and insulin sensitivity, although the evidence is not as strong as those seen for CVD." (PMID 30138332, 2018). "Type 2 diabetes mellitus (T2DM) is a chronic metabolic disease characterized by defects in both β-cell function and insulin sensitivity, which result in elevated blood glucose levels." (PMID 29425121, 2018). "The novel glucose stimulated insulin secretagogues such as 5 GLP-1 analogs, DPP-IV inhibitors, GPR119 agonists and GPR40 agonists have opened new and alternative treatment against Type 2 diabetes." (PMID 29492402, 2018). "Combination therapy with insulin and glucagon-like peptide-1 receptor agonists (GLP-1RAs) is important for treating type 2 diabetes (T2D)." (PMID 29688502, 2018). "During phase II study in a group of patients with NAFLD and type 2 diabetes, OCA improved central and peripheral insulin sensitivity and reduced parameters of hepatic inflammation and fibrosis yielding promising results in larger studies." (PMID 30559664, 2018). "Women with PCOS are commonly insulin resistant (up to 75% of lean and 95% of overweight women with PCOS) and are two to four times more likely to be obese and develop type 2 diabetes." (PMID 30153296, 2018). "However, we have to take into account that these are acute effects observed after transient increases of insulin, whereas in type 2 diabetes hyperinsulinemia is chronic and therefore the long-term effect on Aβ degradation, cognitive function and AD progression could be different." (PMID 29743868, 2018). "According to the selected articles which mentioned the relationship between insulin use and QOL of type 2 diabetes patients, three of them showed that patients who used insulin had a worse QOL than those patient did not use insulin." (PMID 30231882, 2018). "Intriguingly, elevated urinary excretion of 2PY has been suggested as a biomarker of type 2 diabetes progression, and reduced circulating acylcarnitines may reflect maintenance of sufficient mitochondria fatty acid oxidation capacity and preservation of insulin sensitivity." (PMID 29751643, 2018). "Given the increasingly recognized link between AD and defective brain insulin signaling, we investigated the actions of liraglutide, a glucagon‐like peptide‐1 (GLP‐1) analog marketed for treatment of type 2 diabetes, in experimental models of AD." (PMID 29435980, 2018). "Patients with type 2 diabetes (T2D) may need to use insulin as part of treatment to achieve adequate glycemic control." (PMID 29791677, 2018).
type 2 diabetes (continued). "Fasting and 2-h postprandial glucose and insulin, HbA1c, HOMA-IR, triglycerides, ALT and C-reactive protein (CRP) concentrations were significantly increased in subjects with IFG or type 2 diabetes compared to normal subjects (all Ps < 0.05)." (PMID 30532735, 2018). "In addition, recent work supports the involvement of two key factors linking type 2 diabetes mellitus (T2DM) with neurodegeneration; the elevation of proinflammatory cytokines and the onset of insulin/IGF-1 resistance." (PMID 30026694, 2018). "Pancreatic fatty acid uptake and insulin-stimulated glucose uptake as well as fasting serum NEFA concentration were similar in healthy and prediabetic or type 2 diabetic men at baseline and remained unchanged by training." (PMID 29717337, 2018). "One intervention participant with a diagnosis of type 2 diabetes reported hypoglycaemia from week 1 consuming the WFPB diet, and his general practitioner reduced, and then later stopped his insulin." (PMID 28319109, 2017). "More often than not, insulin resistance is overcome by β-cell-induced insulin overproduction; ultimately, the conversion of prediabetes to frank hyperglycaemia in patients having type 2 diabetes becomes linked with a decline in the secretory ability of the overwhelmed pancreatic β-cells." (PMID 28129400, 2017). "The two cohorts of type 2 diabetes patients were similar in baseline characteristics, with the exception that LFC was numerically higher in the insulin naïve cohort." (PMID 28587667, 2017). "ROC AUCs for type 2 diabetes revealed estimates higher than 70% for all early-phase indices, the late-phase index CIR120 and the two overall insulin secretion indices." (PMID 27933333, 2017). "This leads to an exhaustionof β-cell insulin secretion and the development of impaired glucose tolerance(IGT) and subsequent type 2 diabetes." (PMID 28290272, 2017). "In type 2 diabetes, IAPP and insulin secretion is increased to compensate for decreased insulin sensitivity in peripheral tissues, leading to increased local IAPP concentrations and formation of islet amyloid deposits." (PMID 28500395, 2017). "Numerous GPR40 agonists have been generated to increase insulin production from β-cells exposed to hyperglycemia in vivo, and reports this far provide some proof of concept for GPR40 agonists as a treatment for type 2 diabetes." (PMID 28980863, 2017). "Intensive insulin therapy has been used to treat patients with type 2 diabetes (T2D) in China." (PMID 28271075, 2017). "In contrast, significant improvement in glycemia, including insulin sensitivity, was observed during GLP-1 subcutaneous infusion in patients with type 2 diabetes." (PMID 28379519, 2017). "Its future integration with existing models of GLP-1-induced insulin secretion might provide a more reliable description of exercise’s effects on glucose homeostasis and hence support the definition of more tailored interventions for the treatment of type 2 diabetes." (PMID 28704555, 2017). "Understanding how β1 integrin maintains postnatal beta-cell insulin secretion and survival could aid in the development of tissue engineering strategies for a bioartificial endocrine pancreas, a new strategy for cell-based therapeutic approaches for the treatment of both type 1 and type 2 diabetes." (PMID 28968961, 2017). "In humans with type 2 diabetes, the injection of TZD decreased hepatic fat content and increased hepatic insulin sensitivity along with increased glucose uptake by peripheral tissues." (PMID 28781774, 2017). "For instance, overexpression of IAPP relative to insulin has been observed in rat models of type 2 diabetes, and TXNIP has been shown to inhibit insulin transcription while inducing IAPP transcription." (PMID 28980863, 2017). "There is a need to consider cheaper medications than insulin especially in GDM and pregestational type II diabetes." (PMID 28828389, 2017).
type 2 diabetes (continued). "This group had a significantly higher mean HbA1c, number of daily insulin injections, daily insulin dose, and SD around mean SMBG (indicator of glycemic variability) as compared to the group with type 2 diabetes." (PMID 28913365, 2017). "Therefore, regular consumption of a PolyGlycopleX or a psyllium supplement is a simple and effective method to improve blood lipids, insulin and glucose control in overweight or obese people and may lead to risk reduction for metabolic syndrome, CVD and type 2 diabetes." (PMID 28146065, 2017). "In ourstudies, circulating levels of MCP-1 and TNF-α, as well as insulin were greatly elevatedin mice fed on HFD for 15 weeks, indicating a proinflammatory state and insulinresistance seen in type-2 diabetes." (PMID 28076453, 2017). "Their key effect in metabolism is modulating insulin sensitivity, which makes them able to serve as biomarkers of IR and related metabolic disorders, such as NAFLD, type 2 diabetes mellitus (T2DM), and cardiovascular disease (CVD)." (PMID 29291018, 2017). "We analyzed the mechanism regulating insulin signaling during β cell proliferation using the MIN6 mouse insulinoma cell line and db/db mouse model of type 2 diabetes." (PMID 28886131, 2017). "ROC AUCs for incident type 2 diabetes revealed estimates higher than 70% for I30/I0, CP30/CP0, ΔCP30/ΔG30 and corrected insulin response at 30 min (CIR30), with ROC AUCs ranging between 74% and 81%." (PMID 27933333, 2017). "Although we have no data on IL-6, it has been reported that IL-6 can stimulate insulin secretion through glucagon-like peptide-1 (GLP-1) production and secretion in animal models of type 2 diabetes." (PMID 28575103, 2017). "Recent studies have demonstrated that AD has a pathophysiological relationship with type 2 diabetes mellitus (T2DM), in that both involve impairment of insulin signaling and glucose metabolism." (PMID 29165354, 2017). "Conclusively, the impact of insulin on GHR has been inconsistently reported, although the studies collectively show that deregulated insulin, high (e.g., type II diabetes) or low (malnutrition), negatively impacts hepatic GHR levels." (PMID 28486400, 2017). "GLP-1 remains insulinotropic in type 2 diabetes, and this fact has led to the development of compounds that activate the GLP-1 receptor with a view to improving insulin secretion." (PMID 29041949, 2017). "STK25 emerges as a new regulator of the complex interplay between lipid storage, mitochondrial energetics and insulin action in skeletal muscle, highlighting the potential of STK25 antagonists for type 2 diabetes treatment." (PMID 27981357, 2017). "Type 2 diabetes (T2D) is a disease characterized by impaired insulin secretion." (PMID 28851992, 2017). "These in turn may increase type 2 diabetes risk through mechanisms whose effects would not necessarily be detected by measuring fasting blood glucose, such as causing dysfunction in pancreatic cells that secrete insulin." (PMID 28626807, 2017). "Type 2 diabetes mellitus (T2DM) is a heterogeneous group of metabolic disorders including deranged fat, protein, and carbohydrate metabolism and featured by hyperglycemia resulting from insulin resistance and inadequate insulin secretion." (PMID 28904560, 2017). "Type 2 diabetes mellitus (T2DM) is a chronic, progressive disease and diminished insulin sensitivity in peripheral tissues is an important phenomenon in its pathogenesis." (PMID 28983252, 2017). "After removing BMI SNPs, four SNPs were dropped in analyses for type 2 diabetes, three for HDL and fasting insulin, two for two-hour-postchallenge glucose, and one for LDL, total cholesterol, triglycerides, and fasting glucose." (PMID 28954281, 2017). "In the subset for whom calculations of HOMA indices were available (n = 607), urine KTR predicted new onset type 2 diabetes even after adjustment for each of the following: HOMA-B, HOMA-IR, insulin and C-peptide." (PMID 28612106, 2017).